PRL (prolactin)
Diseases named in the same sentence as PRL in open-access papers (continued):
Sharing a sentence is not in itself a finding about the gene and the disease.
diabetes (continued). "After adjusting for age, general obesity, abdominal obesity, diabetes duration, hypertension, glycemic control, dyslipidemia, hyperuricemia, LH, PRL, and estradiol, the negative association between the serum FSH level and NAFLD still remained significant (OR: 0.411, 95% CI: 0.260–0.651, p < .001)." (PMID 37221966, 2023). "T2DM is associated with lower serum PRL levels than those without diabetes mellitus." (PMID 35509763, 2022). "Medications elevating PRL circulating levels may prove to be beneficial in diabetes." (PMID 33746901, 2021). "Also the prolactin signaling pathway disruption has been involved in diabetes." (PMID 33292335, 2020). "Patients with GH–PRL PitNETs are usually more symptomatic, including a higher prevalence of coarse facial features, polyuria and polydipsia, large hands and feet and diabetes mellitus, than GH PitNETs, probably because they show higher levels of IGF1 and PRL." (PMID 37762304, 2023). "In contrast, among non-pregnant, middle-aged populations, higher prolactin levels within the normal range (i.e., 2–18 ng/mL for men and 2–29 ng/mL for non-pregnant women) has been prospectively associated with lower risks of diabetes and impaired glucose regulation." (PMID 32180760, 2020). "Therefore, it is hypothesized that medications causing hyperprolactinemia result in increased ocular PRL and vasoinhibins levels with beneficial outcomes in DR and DME, because of the antagonizing properties of both hormones on diabetes-induced retinal alterations." (PMID 29896154, 2018). "Finally, as our study was cross-sectional and not a cohort study, we could not assess the risk of serum PRL levels on the future incidence of diabetes." (PMID 28384295, 2017). "Prolactin was statistically significantly higher in the group without diabetes [median (25th–75th percentile): 15.12 (7.07; 31.14)] compared to the group with diabetes [7.24 (4.35; 13.18), p = 0.011]." (PMID 40650124, 2025). "Our study also found an increased prolactin value in young people, especially in young patients without diabetes." (PMID 40650124, 2025). "There was an increase in the serum level of progesterone and prolactin in pregnant diabetes women compared to nondiabetes nonpregnant women." (PMID 41013820, 2025). "Thirty participants were analyzed, but 11 were excluded: group 1; did not wish to participate (n = 6), and group 2; high prolactin level (n = 1), diabetes mellitus (n = 2), and did not wish to participate (n = 2)." (PMID 38100407, 2023). "The hazard ratio obtained by the Cox regression analysis for exploring the effect of PRL on the age at the onset of diabetes was close to the RRs obtained from log-binomial models (not shown)." (PMID 36471299, 2022). "The PRL levels were higher in patients with diabetes and no retinopathy (compared to healthy controls) and higher in patients with diabetes and non-proliferative DR than in patients with PDR." (PMID 36157442, 2022). "Consistent with the reduced survival of β-cells, diabetes was exacerbated 11 weeks after STZ treatment in the absence of PRL signaling." (PMID 33746901, 2021). "Because PRL stimulates β-cell mass and function, we sought to evaluate whether STZ-induced diabetes is aggravated in mice null for the PRLR." (PMID 33746901, 2021). "Another study suggests that an increase in normal PRL levels may have a positive effect on BMD in patients with type 2 diabetes mellitus (T2DM) rather than a significant increase in PRL." (PMID 37182163, 2023). "Prolactin can protect β-cells from ER stress through the JAK2/STAT5 pathway, transcription factors such as GLIS3 can enhance INS gene expression, rapamycin can improve diabetes and further down-regulate β-cell apoptosis, and induced pluripotent stem cells can promote β-cell regeneration." (PMID 36686471, 2022).
diabetes (continued). "Early reports found higher PRL levels in patients with diabetes but without severe DR and hypothesized about the potential function of PRL as a protective factor in DR, and about some potential treatment based on the stimulation of PRL secretion." (PMID 36157442, 2022). "Because reversal of diabetes slows down in diabetic Prlr-/- mice, we investigated whether β-cell proliferation was reduced in the absence of PRL signaling 11 weeks after STZ-induced diabetes." (PMID 33746901, 2021). "Preclinical studies support a protective role of the hormone prolactin (PRL) due to its ocular incorporation and conversion to vasoinhibins, a family of PRL fragments that inhibit ischemia-induced retinal angiogenesis and diabetes-derived retinal vasopermeability." (PMID 29896154, 2018). "Furthermore, PRL-expanded Treg (CD4+ Foxp3+) population and improved the efficacy of short-term low-dose anti-CD3 treatment (which induce a transient CD4+ and CD8+ T cell depletion) at achieving diabetes remission in the NOD mice." (PMID 29867762, 2018). "Other than the four adverse events modelled in this study (i.e. weight gain, diabetes, acute EPS and neutropenia), there are other adverse events which might impact on patients’ QALY and cost outcomes, such as tardive dyskinesia, sexual dysfunction, increase in prolactin levels, and agranulocytosis." (PMID 31463768, 2019). "The conversion of PRL to vasoinhibin was mediated by matrix metalloprotease (MMP) present in the vitreous fluid and was higher in patients without diabetes than in patients with PDR." (PMID 36157442, 2022).
acromegaly (90 papers, 2006 to 2026). Acromegaly is an acquired disorder related to excessive production of growth hormone (GH) and characterized by progressive somatic disfigurement (mainly involving the face and extremities) and systemic manifestations. "Our results demonstrate that in male patients with acromegaly, larger tumor diameters are associated with higher levels of GH and PRL, consistent with previous findings, potentially due to the pituitary stalk effect and hormonal co-secretion." (PMID 39707075, 2025). "All tumours causing acromegaly expressed GH, 75% expressed PRL and one tumour showed immunostaining for TSH." (PMID 37851558, 2023). "Acromegaly can also be caused by mammosomatotroph and mature plurihormonal tumors, characterized by expression of GH and additional hormones (prolactin (PRL) or PRL and thyroid-stimulating hormone (TSH), respectively)." (PMID 36497102, 2022). "More than two-thirds of patients present asymptomatic elevations of insulin-like growth factor 1 (IGF-1), GH, and prolactin caused by pituitary hyperplasia, and 10% of patients present with adenomas and symptomatic acromegaly." (PMID 33574795, 2020). "More frequently, positive PRL expression with IHC is encountered as a feature of a silent mixed somatotroph-lactotroph adenoma, a morphological variant of somatotroph adenomas." (PMID 30020466, 2019). "In these patients, acromegaly/gigantism presents very early with excessive GH, frequently associated with high prolactin levels." (PMID 31766255, 2019). "For example, elevated levels of growth hormone (GH) can cause acromegaly or gigantism, increased levels of prolactin (PRL) can result in amenorrhea-galactorrhea syndrome in females or sexual dysfunction in males, and hypercortisolism can cause Cushing’s disease (CD)." (PMID 38716256, 2024). "On the other hand, like any other neuroendocrine tumor, somatotroph adenomas, may intermittently produce prolactin, and they may indicate a wide spectrum of differentiation and variably express prolactin that causes pathological subtypes misclassification, too." (PMID 34530798, 2021). "Our study shows that the predictors of surgical failure and fgSRLs resistance in patients with GH&PRL-PAs are similar to those observed in acromegaly with GH-PAs, including Knosp grade and serum GH and IGF-1 levels at diagnosis as key factors." (PMID 40590355, 2025). "Age, GH, IGF‐I, and PRL levels at acromegaly diagnosis were similar between patients naïve to SRL therapy at surgery and patients treated with SRLs before surgery." (PMID 40789673, 2025). "Consistent with findings from previous series of acromegaly with pure GH-PAs, our study revealed that patients with GH&PRL-PAs who had a Knosp grade >2 along with higher serum GH and IGF-1 levels had an increased probability of surgical failure." (PMID 40590355, 2025). "The two patients with SGSAs had acromegaly, two patients with lactotroph adenomas had clinical and biochemical evidence of prolactin secretion, and of the 5 patients with corticotroph PitNETs/PAs, 4 had confirmed CD." (PMID 40579705, 2025). "A total of 126 acromegaly patients with GH&PRL-PAs who underwent transsphenoidal pituitary surgery were included, and 42.1% (n = 53) were biochemically cured at the immediate postoperative evaluation." (PMID 40590355, 2025). "Dopamine agonists (DAs) are the most effective first-line drugs for treating PRL adenomas due to their functions of inhibiting PRL secretion and reducing tumor size, and DAs are also recommended for acromegaly with mild symptoms." (PMID 38716256, 2024). "There was a dramatic regression of facial features and pituitary lesion volume within 3 months after the removal of the lung NET, with near-normal GHRH and prolactin levels, implicating that the GHRH-secreting lung tumor caused the acromegaly." (PMID 39449742, 2024).
acromegaly (continued). "Particularly, a patient with a DA-resistant PRL-secreting PitNET which evolved into acromegaly has been described, involving an increase in somatotroph cell number in the tumor and the expression of the gsp oncogene." (PMID 37762304, 2023). "In this regard, Andersen reported that 3 cases with PRL-secreting PitNETs out of 78 total patients developed a clinical and biochemical acromegaly after a mean follow-up of 43 months." (PMID 37762304, 2023). "The presence of a prolactin-secreting tumor (OR = 0.224; p = 0.001) and recovery from acromegaly (OR = 0.168; p = 0.006) were independent predictors of LTLs in male acromegaly patients during the follow-up." (PMID 37886642, 2023). "There were significant differences in the BMI, invasion of the cavernous sinus, GH, IGF-1, and prolactin levels at follow-up, occurrence of prolactin-secreting tumors, and recovery from acromegaly between the NTL and LTL groups after surgery." (PMID 37886642, 2023). "Another important point is the possibility of developing acromegaly in patients with a known PRL-secreting PitNET." (PMID 37762304, 2023). "Body mass index, invasion of the cavernous sinus, GH, IGF-1, and prolactin levels, the presence of a prolactin-secreting tumor, and recovery from acromegaly were significantly different (p < 0.05) in the NTL group and in the LTL group during the follow-up." (PMID 37886642, 2023). "The occurrence of a prolactin-secreting tumor (OR = 0.224; p = 0.001) and recovery from acromegaly (OR = 0.168; p = 0.006) were considered to be independent predictors of LTL after surgery." (PMID 37886642, 2023). "Large numbers of acromegaly patients are sporadic GH secreting adenomas that emerged either from somatotrophs or from cells producing GH and prolactin." (PMID 38203605, 2023). "DAs are the first line treatment for PRL-secreting PitNETs but they are also recommended in the treatment of some patients with acromegaly." (PMID 37762304, 2023). "The invasion of the cavernous sinus (OR = 4.299; p = 0.000) and serum prolactin levels (OR = 1.023; p = 0.001) were considered independent predictors of LTLs in male acromegaly patients before surgical intervention." (PMID 37886642, 2023). "Based on this premise, a Consensus of experts recommends measurement of total testosterone, Sex-Hormone Binding Globulin (SHBG) and prolactin for the evaluation of gonadal function in men with acromegaly at diagnosis and then annually." (PMID 35364803, 2022). "Hormone secreting PitNET can cause overproduction of growth hormone (GH), adrenocorticotropic hormone (ACTH), prolactin (PRL) or rarely other hormones leading to various systemic endocrine disorders (acromegaly, Cushing’s disease, and others)." (PMID 36026497, 2022). "The search term was “(Acromegaly OR Growth hormone OR Insulin-like growth hormone-1 OR Prolactin) AND (Hypercalcemia)”." (PMID 33933067, 2021). "We report a case of a 23-year-old male patient who presented with a clinical picture of acromegaly in addition to raised prolactin level." (PMID 32455041, 2020). "While densely-granulated somatotroph tumors are the most common cause of acromegaly in adults, mammosomatotroph tumors that produce both GH and prolactin are the most frequent tumors in young patients with acromegaly and in cases of childhood onset-gigantism." (PMID 31766255, 2019). "Patients with prolactin co-secretion were significantly younger at diagnosis than other acromegaly patients." (PMID 28733467, 2017). "Six of the prospectively diagnosed patients had acromegaly (one of them with prolactin [PRL] cosecretion), one patient had gigantism, two patients were diagnosed with mild acromegaly, and nine patients harbored NFPAs." (PMID 26186299, 2015). "Our patient was treated with a bisphosphonate and the prolactin antagonist, cabergoline, resulting in the inhibition of fibrous dysplasia and involution of both the prolactinoma and growth hormone excess." (PMID 22273876, 2012).
acromegaly (continued). "Growth hormone (GH) and prolactin (PRL) co-secretion may be present in approximately 15–40% of all acromegaly cases, depending on the employed definition for co-secretion." (PMID 40590355, 2025). "This difference may be attributed to systemic hormonal imbalance in acromegaly, the pleiotropic and multidirectional role of PRL across biological systems, and methodological discrepancies." (PMID 41141060, 2025). "Additionally, approximately 16–27% of acromegaly patients present elevated GH and prolactin (PRL) levels." (PMID 40421250, 2025). "Acromegaly patients with GH&PRL-PAs included in the ACRO-SPAIN study were enrolled." (PMID 40590355, 2025). "On the other hand, hormonally active tumors gave symptoms dependent on secreted hormones, i.e., lactotroph—mainly menstrual disorders in women; corticotroph—symptoms resulting from hypercorticism; somatotroph—symptoms of acromegaly; mature Pit-1-lineage tumor—mainly symptoms of excess PRL and GH." (PMID 40002261, 2025). "It is interesting to speculate that PRL dominates over other sex hormones and inhibits gonadotropins in female patients with acromegaly, leading to the preoperative decrease in E2 and TT levels." (PMID 39707075, 2025). "In the latest multicenter retrospective study conducted on 604 acromegaly patients, the authors suggested that cosecreting tumors should be considered when the tumors stained positive for GH and PRL with elevated PRL levels or serum PRL levels above 100 ng/dL, regardless of the IHC result of PRL." (PMID 40421250, 2025). "Meanwhile, dopamine agonists are more effective at treating acromegaly in prolactin co-secretion." (PMID 38279102, 2024). "Functional tumors might lead to endocrine disorders, such as pituitary‐dependent hyperadrenocorticism, acromegaly, increased prolactin production, or the tumors can be plurihormonal." (PMID 37084035, 2023). "In fact, while densely granulated somatotroph tumors has been found as the most frequent cause of acromegaly in adults, mammosomatotroph tumors producing GH and PRL have been reported as the most common tumors in young patients with acromegaly and in cases of childhood-onset gigantism." (PMID 37762304, 2023). "A retrospective study was conducted with 32 consecutive cases of PRL- and mixed GH- and PRL-secreting PitNETs (5 patients with prolactinomas and 27 with acromegaly, among them, 7 patients with GH- and PRL- co-secretion) who underwent transsphenoidal intervention." (PMID 38003353, 2023). "Referring to the anatomical pathology of the 4 patients who underwent surgical removal, patient 4 had hormonal immunohistochemical expression and transcription factors compatible with sparsely granulated somatotrophic adenoma, with a prolactin expression focus." (PMID 37908013, 2023). "Almost half of GH-producing PitNETs (acromegaly) simultaneously secrete PRL." (PMID 35892862, 2022). "Younger age at diagnosis, male sex, lower GH, IGF-1 and PRL concentrations, smaller tumor size at diagnosis as well as positive α-SU staining, lower Ki-67 index and DG tumors predicted better treatment outcome in acromegaly patients." (PMID 36187106, 2022). "Moreover, we demonstrate for the first time that in vitro PEG inhibits GH secretion of human somatotroph adenomas and PRL release of mixed GH/PRL adenomas." (PMID 27267119, 2016). "Additionally, mRNA for both GH and PRL has been detected in the tumors of patients with a clinical diagnosis of acromegaly or gigantism." (PMID 26106585, 2015). "Pituitary histopathologic findings revealed pure GH-producing somatotroph adenomas (SA) in 147 patients, prolactin-production by mixed lactotroph (LA) and SA or mammosomatotroph adenoma (MSA) in 46 [22.4%], acidophil stem cell adenoma in 6 [2.9%], and other diagnoses in 6 [2.9%]." (PMID 24039977, 2013).